CD4 (CD4 molecule)
Diseases named in the same sentence as CD4 in open-access papers (continued):
Sharing a sentence is not in itself a finding about the gene and the disease.
colitis (continued). "On the other hand, the same treatment did not rescue severity of colitis driven by WT CD4+ T cells." (PMID 40303402, 2025). "GSSSG administration ameliorated colitis induced by Cars2+/- but not WT CD4+ T cells." (PMID 40303402, 2025). "Indeed, CD4+ T cells with reduced levels of CARS2/CPERS exhibited accelerated cell cycle entry and induced severer colitis in Rag2-/- mice, and treatment with GSSSG, an endogenous donor of supersulfide that is generated by CARS2/CPERS, ameliorated inflammation." (PMID 40303402, 2025). "We performed adoptive transfers of P440S CD4+ T cells into immunodeficient-RAG KO mice to test whether these cells are sufficient to induce colitis (data not shown)." (PMID 37962568, 2024). "This hypothesis is supported by our finding that the protective effect of liver cholestasis on colitis severity was not detectable in the CD4+CD45RBhigh T-cell transfer colitis model, 45 in which Foxp3+ Treg cells are largely absent." (PMID 38839272, 2024). "In addition, in an adoptive CD4+ T cell transfer colitis model, co-transferred NCOR1-cKO Treg cells even failed to protect recipient mice from weight loss and intestinal tissue damage in comparison to co-transferred WT Treg cells." (PMID 39466314, 2024). "Collectively, these findings indicated a novel and previously unknown role played by IL-21/IL-21R signaling in driving CD4+ T-cell responsiveness to IL-12 by enhancing the expression of IL-12Rβ2 in CD4+ T cells, thereby imprinting a TH1-biased immunity during bacterial-induced colitis." (PMID 38498592, 2024). "However, its impact on the polarization of CD4+ and/or CD8+ T cell subsets in the context of colitis remains unclear." (PMID 39116526, 2024). "However, irrespective of the rBanLec treatment, the pool of CD4+ lymphocytes within MLNs collected from C57BL/6 mice subjected to the induction of experimental colitis showed a higher percentage of Treg at the peak of the disease compared to NC (p ˂ 0.05)." (PMID 38892639, 2024). "Consistent with the intracellular production levels of IFN-γ in CD4 T cells, the concentration of IFN-γ in the culture medium of CD4- and FimH-stimulated CD11b+CD103- DCs was considerably upregulated compared to that in PBS-treated CD11b+CD103- DCs from DSS-colitis mice." (PMID 38077339, 2023). "Similarly, HS intake in mice resulted in an enhanced inflammatory response in terms of cytokine production (pro-inflammatory TNF-α, IL-17A, and IL-23), increased IL-23R+CD4 T cells, MAP, and exacerbated colitis in mice with artificially induced inflammatory bowel disease (IBD)." (PMID 37108475, 2023). "Importantly, the PELNs-Lactobacillus reuteri-indole-derivatives axis played a crucial role in downregulating the expression of Zbtb7b in conventional CD4+ T cells, resulting in the reprogramming of conventional CD4+ T cells into DP CD4+CD8+ T cells and subsequently alleviating colitis in mice." (PMID 37653406, 2023). "CD4+ T cells from mice lacking epithelial HDAC3 induce severe colitis." (PMID 36602872, 2023). "While treatment with tofacitinib immediately after transfer resulted in an enhanced expansion of CD4+ T cells and did not prevent occurrence of colitis, treatment after start of symptoms of colitis ameliorated disease activity on a clinical basis and in histological analyses." (PMID 36882462, 2023). "Notably, there was an increase in the proportion of infiltrated immune cells (CD45+), CD4+ and CD8+ T cells, macrophages (CD11b+F4/80+), and neutrophils (CD11b+Gr1+) in Smad4−/− mice during colitis compared with those in WT mice, which was accompanied by enhanced IFNγ levels." (PMID 37261975, 2023). "The frequency of CD4+IL-4+ Th2 cells was mildly reduced after induction of colitis by DSS, which did not change with or without cADSC administration (control: 3.0% ± 0.1%; PBS: 2.3% ± 0.6%; primary: 2.1% ± 2.2%; cADSC-K4DT: 2.2% ± 0.2%; cADSC-K4D: 2.7% ± 1.1%)." (PMID 38139314, 2023).
colitis (continued). "Indeed, patients with ipilimumab-mediated colitis tend to have a higher absolute count of peripheral CD4 T-cells and a lower percentage of regulatory T-cells at baseline than patients without colitis." (PMID 38201577, 2023). "In addition, TRPA1 was also detected in CD4+ T-cells infiltrating colon tissue samples from patients with UC and CD, and TRPA1 is involved in the control of CD4+ T-cell activation and proinflammatory responses in two different T-cell-mediated colitis models." (PMID 37039840, 2023). "However, DSS-colitis was shown to be independent of the production of IL-17 within lamina propria CD4+ T cells, where neutralisation of IL-17A in prototypical Th2 biased BALB/c mice aggravated disease." (PMID 36012618, 2022). "ALKBH5, not FTO, promotes naïve CD4+ T cells to induce adoptive transfer colitis." (PMID 36225914, 2022). "Animal studies of colitis had demonstrated that B. fragilis NCTC 9343, B. thetaiotaomicron DSM 2079, and B. cellulosilyticus DSM 14838 improved intestinal histopathological injury and increased anti-inflammatory cytokine IL-10 and Treg cells levels by increasing the number of CD4+ CD45RBlow T cells." (PMID 36531989, 2022). "Oral administration of synthetic ODN (ID35) derived from L. rhamnosus attenuated colitis, and a synthetic ODN derived from Streptococcus thermophilus NCDO 573 (commonly found in fermented milk products) increased IL-10 expression and proportion of CD4+CD25+ Treg in murine splenocytes." (PMID 35529463, 2022). "Interestingly, the proliferative CD4+ T cell expansion was also seen in both responders and nonresponders who developed severe colitis, suggesting that this expansion was independent of the response status." (PMID 36173679, 2022). "Therefore, the activation of α7nAChRs inhibits the migration of pathogenic pDCs into ILFs in the colonic mucosa of OXZ mice, thereby suppressing the activation of Th2 CD4+ T cells in ILFs, their homing to inflamed sites in the colonic mucosa of OXZ mice and, eventually, the development of colitis." (PMID 34997096, 2022). "When Tregs were transferred with naïve CD4 T-cells colitis did not occur." (PMID 35633761, 2022). "Similarly, a significant expansion of proliferative CD4+ T cells was apparent in those who developed colitis but not in those who did not." (PMID 36173679, 2022). "Therefore, over-expression of Zbtb7b might repress the differentiation of DP CD4+CD8+ T cells and then increase the production of inflammatory cytokines, such as TNF-α, IL-17, and IFN-γ, in the DSS-induced colitis model." (PMID 35761286, 2022). "By using a T cell-dependent mouse colitis model in which colitis is induced by adoptive transfer of naive CD4+ T cells into immunodeficient mice, EBI3-deficient naive CD4+ T cells failed to induce colitis with reduced interferon (IFN)-γ production in the intestinal lamina propria lymphocytes." (PMID 34603342, 2021). "In addition to CD4+ and CD8+ cells, αEβ7 was found upregulated on a subset of γδ-T lymphocytes found in the mesenteric lymph node and the intestinal tissue in a mouse model of T cell-mediated colitis and the SAMP spontaneous chronic ileitis." (PMID 34638778, 2021). "The results showed that percentages of CD4+CXCR5+PD-1+ Tfh and Tfh/Tfr ratios in the MLNs and spleen of colitis mice increased significantly compared to those of normal mice (p < 0.05), while no statistical difference was found in CD4+CXCR5+Foxp3+ Tfr (p > 0.05)." (PMID 34707499, 2021). "In the T cell transfer mouse model of colitis, the transfer of CD4+ T cells lacking both Hobit and Blimp-1, which are two transcription factors associated with mouse TRM cells, into lymphopenic Rag2−/− mice was not able to induce colitis to the same extent as with wildtype CD4+ T cell transfer." (PMID 34440651, 2021).
colitis (continued). "In this model, immunodeficient mice lacking mature T and B cells (e.g., Rag1 -/-) develop colitis a few weeks following the transfer of naïve CD4+ T cells (CD25negCD45RBhigh) unless a fraction containing Treg cells (e.g., CD45RBlow or CD4+CD25+FOXP3+) are co-injected." (PMID 34421921, 2021). "Furthermore, increased sensitivity to DSS-induced colitis was observed in Traf5-/- mice, and might be attributed to enhanced Th2 and IFN-γ/IL-17A co-producing CD4+T cell responses and CD4+T cell NF-κB activation under intestinal inflammation." (PMID 34956195, 2021). "Most importantly, we observed a significant increase in enteric CD4+ T cells (integrin α4β7 positive), especially Th17 and Th1 cells in the PLNs of WT mice but not KO mice with colitis." (PMID 35111148, 2021). "Furthermore, the infiltration of CD4+ T cells, CD8+ T cells, and CD19+ B cells in the colonic lamina propria remained unchanged upon the tiliroside (12.5, 25.0, and 50.0 mg/kg) administration in the DSS-induced colitis mice." (PMID 33868286, 2021). "Notably, cotransfer of naive WT CD4+ T cells and Cd25Y129H Treg cells into Rag2−/− recipients did not prevent the development of colitis as efficiently as cotransfer of WT Treg cells." (PMID 33408345, 2021). "Our observations thus suggest that PD-1/PD-L1 CBI may interfere with epithelial constraints on CD4+ TRM cells and unleash unrestrained TRM cell activation leading to immunopathologies like CIP, colitis, IBD, and skin inflammation, all of which may involve CD4+ T cell plasticity." (PMID 34611166, 2021). "We analyzed the microbiome of the CD4-Cre+/TgMettl14FL/FL conditional knockout mice that had developed severe colitis and compared them to the microbiome of WT littermate control mice that do not have colitis." (PMID 32634481, 2020). "Interestingly, however, Plac8-/- CD4 T cells did not induce enhanced morbidity compared to Plac8+/+ CD4 T cells in a T cell transfer model of colitis in which Th1 cells are important mediators of disease." (PMID 32639988, 2020). "More importantly, predominant Th1 and Th17 responses present as colitis-related abundant CD4+ IFN-γ+ Th1 and CD4+ IL17+ Th17 cells that infiltrate into the colon mucosa LP, and colitis-mediated upregulated IFN-γ and IL-17A mRNA transcripts in the intestinal tissues were found in colitis mice." (PMID 32855978, 2020). "This may be because IL-12p70 is known to be dispensable for colitis, but IL-23 and IFNγ are not, suggesting that IFNγ production by CD4 T cells may result from IL-23 stimulation rather than IL-12 stimulation in this model." (PMID 32639988, 2020). "Compared with the normal group, the numbers of CD4+CXCR5+BCL-6+, CD4+CXCR5+ICOS+, CD4+CXCR5+PD-1+, and CD4+CXCR5+PD-L1+ T cells were significantly elevated, while CD4+CXCR5+Blimp-1+ T cells were inhibited in the peripheral blood of colitis mice in the DSS group." (PMID 32581849, 2020). "The levels of effector memory T cells, such as CD4+CD62L− (CD4+TEM) T cells, and the expression of the homing cell adhesion molecule CD44 in the peripheral blood, spleen, lamina propria of the small intestine, and mesenteric lymph nodes of mice with colitis were found to be decreased." (PMID 33597887, 2020). "After the mice with colitis were treated with curcumin and mesalazine, the number of TEM cells (Figures 4C1–5) was significantly higher than that in mice with untreated colitis, while the number of CD4+ TEM (Figures 4D1–5) and CD8+ TEM cells (Figures 4E1–5) decreased significantly." (PMID 33597887, 2020). "In this study, the classic and pathological changes of DSS-induced colitis were synchronously observed with low numbers of Tcm cells followed by over-differentiation of CD4+ and CD8+ Tcm cells and high numbers of Tem cells followed by imbalance of CD4+ Tem/CD8+ Tem cells." (PMID 32714185, 2020). "Therefore, reduced engraftment is not the reason for decreased colitis in adoptive transferal of TRAIL-treated CD4 T cells." (PMID 31076664, 2019).
colitis (continued). "Therefore, we compared the ATP production in BBR-treated colitis LP CD4+ T cells to that of non-BBR-treated colitis LP CD4+ T cells." (PMID 31417110, 2019). "Moreover, no report has addressed the ASC requirement in CD4+ T cells during colitis, and thus, our results are not comparable." (PMID 31379813, 2019). "In addition, the phenotype of disease in Rag1−/− mice receiving Nlrp3−/− or Casp-1−/− CD4+ T cells did not resemble the exacerbated colitis observed in mice receiving Asc−/− CD4+ T cells." (PMID 31379813, 2019). "Thus, in the T cell transfer colitis model dietary iron reduction had no influence on the accumulation of CD4+ T cells in the colon, mLN and spleen and their capacity to produce IFN-γ and IL-17 was not affected." (PMID 31276514, 2019). "We noted that the percentages of CD3e+CD4+CD25+Foxp3+ cells in the spleens of mice with DSS-induced colitis that were treated with M2b macrophage exosomes were significantly increased (12.7 ± 0.7%; P < 0.05), compared with those in the spleens of PBS-treated mice with DSS-induced colitis (9.3 ± 1%)." (PMID 31749791, 2019). "Here the authors show that Stat1 also serves to protect CD4 T cells from natural killer cell-mediated killing, potentially by promoting the expression of Nlrc5 and MHC-I, to preserve the induction of experimental colitis via the adoptive transfer of CD4 T cells." (PMID 30796216, 2019). "In colon, considering the low frequency of CD4+ Tcm cells in CD25−/− mice and unchanged PD-1 expression on CD4+ T cells after CXCR3 deletion, we proposed that the reduced migration of PD-1+ CD4+ T cells into the colon is primarily responsible for alleviated colitis." (PMID 29868034, 2018). "In addition, the population of CD4+CD25+Foxp3+ Tregs in the peripheral blood was significantly upregulated in the pretreated-Bifico-colitis and pretreated + treated-Bifico-colitis groups compared with the colitis group (P < 0.05 for both)." (PMID 29849501, 2018). "Importantly, transfer of naïve CD4+ T cells into germ free mice does not induce colitis indicating that inflammation in the gut results from a dysregulated immune response toward commensal microbes." (PMID 30662436, 2018). "In the absence of IFNγ, intestinal inflammation in CD4 T cell recipient mice was associated with enhanced IL17 responses; consequently, targeting IL17 signaling in IFNγ-deficient mice reduced T cell-mediated colitis." (PMID 29416538, 2018). "Furthermore, anti-IL17A treatment failed to attenuate colitis induced by adoptive transfer of Tbx21−/− CD4 T cells in Rag1−/− recipients." (PMID 29416538, 2018). "In order to determine whether enhanced inflammation and tissue destruction of the epithelial barrier during DSS colitis is causative of enhanced activation-dependent potential of Nr2f6−/− CD4+ (CD25−CD62LhiCD44lo) T cells, we used a model of T cell-dependent colitis." (PMID 28779026, 2018). "Furthermore, Cccdc88b mutant mice are protected against DSS-induced colitis, and naive Ccdc88b mutant CD4+ T cells do not induce colitis in immunocompromised mice." (PMID 29030607, 2017). "Therefore, the aim of our study was to evaluate the effect of CS on the course of intestinal inflammation and differences in complete blood count (CBC) and subpopulations of lymphocytes in the blood (CD4+, CD8+, CD19+) and colon (CD4+, CD8+, CD20+) in animal model of DSS-induced colitis." (PMID 28812128, 2017). "Previous studies have determined that S. japonicum-secreted Sj-Cys could stimulate CD4+CD25+Foxp3+ Treg cells, alleviate the Th1 dominated immunopathogenesis and actively restrain the colonic inflammation in TNBS-induced experimental colitis in mice." (PMID 28482922, 2017). "However, the effector CD4+ T cells themselves do not seem to be responsible for the induction of colitis, as their numbers as well as their production of the inflammatory cytokines IFN-γ and IL-17A are significantly reduced." (PMID 28452361, 2017).
colitis (continued). "However, transfer of Bcl-3TOE CD4+CD25− T cells failed to induce colitis in RAG1−/− recipients, whereas control CD4+CD25− T cells induced colitis as measured by significantly increased clinical scores of intestinal inflammation and weight loss." (PMID 28452361, 2017). "In a murine model of chronic colitis induced by adoptive transfer of CD4+CD45RBhi T cells, PD-L1 blockade treatment before (but not after) the onset of severe colitis suppressed T cell expansion and Th1 cytokine production and prevented the development of colitis." (PMID 29255458, 2017). "In this study, CD4+CD25+Foxp3− cells and the production of IL-10 significantly decreased in IL-21RKO mice with DSS-induced colitis, which may contribute to aggravate the development of colitis." (PMID 27545302, 2016). "However, recent studies show that T cells especially pro-inflammatory, antigen-specific CD4+ T cells accumulate at the site of inflammation, and do progress during DSS-induced colitis model, suggesting that DSS model can be used to study T cell development during intestinal inflammation." (PMID 27128484, 2016). "Moreover, following wild type CD4+ T-cell transfer, Rag2−/− mice lacking both IL-10 and IL-22 signaling develop severe colitis, which cannot be rescued by exogenous IL-10." (PMID 27027442, 2016). "The failure to afford colitis protection using larger numbers of naïve CD4+ T cells could, alternatively, be secondary to the lack of relevant immune cell types required to expand Treg cell numbers in vivo." (PMID 27353032, 2016). "We previously reported that TAK1 deficiency in T cells resulted in an impaired generation of regulatory T cells and in fact we confirmed a dramatic reduction in the frequency of CD25+Foxp3+ cells in CD4 single positive thymocytes of 6-week-old LTAC mice in which colitis does not appear." (PMID 26132627, 2015). "The CD4+CD62L− cells from germ-free animals were not able to suppress the colitis." (PMID 25666708, 2015). "Indeed, transfer of wild-type CD4+CD25+ Treg cells into Gimap5sph/sph early on prolonged survival, prevented increased CD4+ T cell effector function in the MLN, and protected these mice from colitis." (PMID 25944983, 2015). "Another study showed that animals received cells from germ free mice developed an earlier onset of colitis, and CD4+CD62L− cells from germ free mice were not able to ameliorate colitis compared with mice reconstituted with lymphocytes from conventionally housed animals." (PMID 25849657, 2015). "Taken together, we conclude that the exchange of β5i/LMP7 for β5 in T cells does not abolish but may modulate CD4+ T-cell mediated disease, with aggravating effects on inflammation in case of T-cell transfer-induced colitis." (PMID 24740379, 2014). "Furthermore, it has been recently reported that a novel subset of helper CD4+ T cells producing IL-17A, namely Th17 cells, is involved in progression of DSS-induced colitis, although an IL-17-mediated protective effect on the Th1-type colitis model has recently been reported." (PMID 24686517, 2014). "Thus, in the T-cell transfer model, β2i/MECL-1&β5i/LMP7-deficiency in transferred, naïve CD4+ T-cells enhances colitis development in RAG1−/− mice, whereas immunosubunit-deficiency in the targeted gut does not have any effect on colitis development." (PMID 24740379, 2014). "Results from IEL T cell analyses in prolapse-free CD4cre:PP4f/f mice, from helper T cell polarization, and from the induction of experiment colitis also helps rule out the possibility that PP4 deficiency induces novel pro-inflammatory, colitogenic effector CD4 T cells." (PMID 24904742, 2014). "RAG-2−/− LP CD4+ mice exhibited severe colitis without infiltration of T cells in the liver." (PMID 24392145, 2014).